IL6 (interleukin 6)
Diseases named in the same sentence as IL6 in open-access papers (continued):
Sharing a sentence is not in itself a finding about the gene and the disease.
osteosarcoma (continued). "Our findings show that TIMP3 levels correlated positively with cisplatin sensitivity in osteosarcoma, which is regulated by the IL-6/TIMP3/Caspase pathway in vitro and in vivo." (PMID 29731768, 2018). "In another model of osteosarcoma, mesenchymal stem cell media promoted chemoresistance via IL6 secretion." (PMID 29930760, 2018). "In brief, osteosarcoma cells produce soluble osteolytic factors such as interleukin-6 (IL-6), IL-11, tumor necrosis factor-α, or receptor activator of NF-κB ligand (RANKL) that activate osteoclastogenesis, leading to bone degradation." (PMID 29761075, 2018). "In a separate study, IL-6-dependent Stat3 activation in mesenchymal stem cell-derived osteosarcoma cells protects tumor cells from drug-induced apoptosis, and promoted proliferation and metastasis." (PMID 28054649, 2017). "Another study on osteosarcoma revealed that ICAM-1 is upregulated by interleukin-6 and is responsible for the migration of osteosarcoma cells." (PMID 28903329, 2017). "In this study, we report that IL-6 suppression inhibits in vitro and in vivo osteosarcoma growth and metastasis." (PMID 26623559, 2016). "We observed that the expression of IL-6 was higher in the resistant osteosarcoma samples as compared to the sensitive samples." (PMID 27340780, 2016). "We previously demonstrated that primary osteosarcoma cells (SOSP-9607) secreted more IL-6 than did CTCs (F5M2 or F4 cells)." (PMID 26623559, 2016). "High IL-6 expression significantly correlated with postoperative recurrence in clinical osteosarcoma specimens (P < 0.05)." (PMID 26623559, 2016). "Using MTT and cell colony formation assays, we determined that IL-6 knockdown suppressed the proliferation of osteosarcoma cells." (PMID 26623559, 2016). "To further investigate the correlation between IL-6 and tumour self-seeding in clinical osteosarcoma patients, we evaluated IL-6 immunohistochemistry in specimens from patients with postoperative recurrence and from patients undergoing a first operation." (PMID 26623559, 2016). "Our study further demonstrated that IL-6 expressed by primary osteosarcoma cells had a stronger effect in promoting growth and metastasis." (PMID 26623559, 2016). "We evaluated IL-6 immunohistochemical staining in clinical osteosarcoma specimens from 11 patients with postoperative recurrence and 29 patients with a first operation." (PMID 26623559, 2016). "In this study, we measured IL-6 expression in tumour cells and found that all osteosarcoma cells expressed IL-6." (PMID 26623559, 2016). "Cytokines such as interleukin 6 (IL-6), which is secreted by osteosarcoma cells, promote CTC recruitment and seeding." (PMID 26623559, 2016). "To investigate the role of IL-6 in tumour self-seeding, we reduced IL-6 levels in primary osteosarcoma cells." (PMID 26623559, 2016). "Interleukins and their receptors also showed higher expression in MSCs compared to both sarcomas, except for IL6 and its receptor IL6Ra in osteosarcoma, suggesting the possible involvement of IL6 signaling in osteosarcoma development." (PMID 22852096, 2012). "During the initial stages of osteosarcoma invasion, growth factors such as TGF-β are released from the degraded bone matrix and act on osteosarcoma cells, stimulating the release of PTHrP, interleukin-6 (IL-6) and interleukin-11 (IL-11)." (PMID 21559216, 2011). "We have studied the expression of interleukin-6 induced by interleukin-1 β and tumor necrosis factor α in the osteoblast-like cell line MG-63, derived from a human osteosarcoma." (PMID 23675187, 2010). "Dadzein, like E2, inhibited IL-1β-cytokinin- and hormone-mediated IL6 (interleukin-6; a multifunctional inflammatory cytokine) secretion from G-209 osteosarcoma cell lines." (PMID 21217857, 2009). "For example, IL-6 mediated activation of the JAK/STAT3 pathway has been shown to be closely associated with enhanced immune suppression and accelerated tumor development in osteosarcoma." (PMID 40959080, 2025).
osteosarcoma (continued). "IL‐6 secreted by RB1‐dependent senescent osteoblasts following ionising radiation actives NKT cell enrichment along with a host inflammatory response, and mice devoid of IL‐6 or NKT cells demonstrate a rapid progression in the development of IR‐induced osteosarcomas." (PMID 39270064, 2024). "Additionally, Infliximab has also been shown to inhibit IL-1β and IL-6 gene expression in the human osteosarcoma cell line MG-63." (PMID 39596421, 2024). "In addition, in osteosarcoma, a function of IL-6 in the acquisition and maintenance of stemness characteristics was described." (PMID 37685940, 2023). "Gross et all,reported a self- seeding osteosarcoma by chemotaxis and IL-6 production." (PMID 37031192, 2023). "The expression of IL-6 in 104 osteosarcoma samples was tested by IHC." (PMID 37404767, 2023). "Moreover, lncRNA ODRUL acted as a sponge of miR-6874-3p to elevate the expression of IL-6, leading to osteosarcoma progression." (PMID 35992869, 2022). "Furthermore, there is evidence that autocrine IL-6 production is an important element in tumour metastasis and enhancement of cell migration and invasion in human chondrosarcoma and osteosarcoma." (PMID 35484352, 2022). "In addition to its functions on the tumor microenvironment (e.g., bone and immune cells), the IL-6 signaling pathway controls the maintenance of CSCs in osteosarcoma." (PMID 35582537, 2022). "Our data indicated that doxorubicin enhanced IL-1β and IL-6 levels in osteosarcoma." (PMID 35326493, 2022). "The use of active drugs confirmed the contribution of the IL-6/STAT3 axis in osteosarcoma stemness." (PMID 35582537, 2022). "Our proteomics-based study as well as PRM validation demonstrated that hFXR1p is a prominently increased protein in the rhILG compared with the LG, indicating that hFXR1p may be involved in lobaplatin resistance induced by exogenous IL-6 in osteosarcoma cells." (PMID 33791202, 2021). "In this study, we investigated the differential protein expression after recombinant human IL-6 (rhIL-6) intervention before lobaplatin treatment of an osteosarcoma SaOS-2 cell model and revealed potential biomarkers that indicate the decreased sensitivity of osteosarcoma to lobaplatin." (PMID 33791202, 2021). "Moreover, vesicular TGF-β induces proinflammatory IL-6 production by MSCs, allowing the tumor EV-educated mesenchymal stem cells to promote osteosarcoma progression together with intratumor STAT3 activation and lung metastasis formation." (PMID 34830463, 2021). "In the future, advanced imaging systems for the measurement of tumour glycolysis and/or pH may help identify osteosarcoma patients who would benefit from anti-IL6 therapies to complement conventional therapy." (PMID 34831016, 2021). "The GO enrichment analysis suggested that IL-6 pretreatment before lobaplatin treatment significantly regulated kinase binding, Toll-like receptors, Hippo signaling, and mitogen-activated protein kinase binding (all p-values < 0.05) in osteosarcoma cells." (PMID 34717622, 2021). "Additionally, according to previous studies, IL-6 is involved in resistance to chemotherapy in osteosarcoma cells in vitro." (PMID 34717622, 2021). "Finally, by using 3D microfluidic models, we directly showed the promotion of osteosarcoma invasiveness by acidosis via IL6 and MSC." (PMID 34831016, 2021). "Similarly, EVs originating from osteosarcoma cells carry a high level of TGF-β1, which causes MSCs to secrete interleukin-6 (IL-6)." (PMID 33081785, 2020). "Interleukin-6, secreted by MSCs, contributes to promote metastatic dissemination of osteosarcoma." (PMID 31370265, 2019). "We aimed to investigate the crosstalk between IL-6 and TIMP3, and to determine whether TIMP3 influences cisplatin sensitivity, proliferation, migration, and invasion of osteosarcoma cells to reveal the mechanisms underlying osteosarcoma drug resistance." (PMID 29731768, 2018).
osteosarcoma (continued). "In addition, irisin inhibits the proliferation, migration, and invasion of osteosarcoma cells and reverses the IL-6 induced EMT in osteosarcoma cells via the STAT3–Snail signaling pathway." (PMID 30323244, 2018). "To determine whether CUL4B is specifically regulated by NF‐κB in osteosarcoma cells, we selected IL‐6, CXCL5, and CCR5 as representatives to monitor their expression in U2OS, MG63, Saos‐2, and HOS cells." (PMID 29377600, 2018). "Our previous study demonstrated that tumour self-seeding occurs in osteosarcoma nude mouse models and that IL-6 might accelerate this process." (PMID 26623559, 2016). "Mesenchymal stem cells (MSCs) promote osteosarcoma proliferation and metastasis by secreting IL-6." (PMID 26623559, 2016). "Then we examined the effects of MSC-produced IL-6 on osteosarcoma cells." (PMID 27340780, 2016). "We established primary tumours using osteosarcoma cells and their IL-6 knockdown counterparts." (PMID 26623559, 2016). "Thus, high IL-6 expression closely correlated with postoperative recurrence in osteosarcoma patients." (PMID 26623559, 2016). "Moreover, Transwell migration and invasion assays showed that IL-6 knockdown decreased both the migration and invasion of osteosarcoma cells in vitro." (PMID 26623559, 2016). "Previously, we demonstrated that tumour self-seeding by CTCs occurs in osteosarcoma and revealed that interleukin-6 (IL-6) may promote CTC attraction." (PMID 26623559, 2016). "On the other hand, interleukin (IL)-6 enhanced osteosarcoma migration involves ICAM-1 expression." (PMID 23803661, 2013). "In addition to cancer metastasis, a similar signal pathway involving ASK1-dependent JNK/p38 activation was reported to be involved in IL-6 induced angiogenesis and metastasis in osteosarcomas." (PMID 23892595, 2013). "Thus, to compare the action of these cytokines in the osteosarcoma cell line MG-63, we have first monitored the profile of IL-6 mRNA accumulation as a function of time, measuring the steady-state level of the transcript." (PMID 23675187, 2010). "MSCs and osteosarcoma cells then established a reciprocal dialog initiated by TGF-β containing extracellular vesicles secreted by cancer cells that induced the production of IL-6 by MSCs, which in turn supported stemness, drug resistance, and tumor progression." (PMID 35582537, 2022). "However, the underlying comprehensive mechanism of IL-6 treatment on the decreased sensitivity to platinum-based chemotherapeutics in osteosarcoma cells has not yet been systemically elucidated." (PMID 33791202, 2021). "Diosmetin markedly inhibited the proliferation ability of osteosarcoma cells, while IL-6 administration, which could simulate STAT3 signaling activation, counteracted diosmetin-induced anti-osteosarcoma effect and significantly, although partly, reverse proliferation of Saos-2 or U2OS cells." (PMID 34922636, 2021). "Therefore, blocking of STAT3 signaling by AG490, a JAK2 inhibitor, or the knockdown of IL-6 using siRNA could re-sensitized drug-resistant osteosarcoma cells to doxorubicin and cisplatin." (PMID 34198693, 2021). "Notably, tumor acidosis is also an important pro-tumor factor, which may promote survival, chemoresistance and stemness of osteosarcoma cells by acting directly in tumor cells or by activating the NFκB/IL6 axis in MSCs." (PMID 34198693, 2021). "Our previous research suggests that IL-6 may contribute to the survival of osteosarcoma cells." (PMID 27340780, 2016). "Thus, IL-6 increased the proliferation, migration, and invasion of osteosarcoma cells in vitro." (PMID 26623559, 2016). "In osteosarcoma, DLGAP5 has been demonstrated to promote tumor development via the IL-6/JAK2/STAT3 signaling pathway." (PMID 40181976, 2025). "Several TAM derived chemokines and interleukins including TGFβ, IL6, IL10, CCL2 and CCL18 are essential for metastatic bone sarcoma with most studies performed in osteosarcoma." (PMID 40442778, 2025).
osteosarcoma (continued). "Network pharmacology showed that 251 luteolin against osteosarcoma targets and 8 hub targets including AKT1, ALB, CASP3, IL6, JUN, STAT3, TNF, and VEGFA." (PMID 40066267, 2025). "Next, we investigated the correlation between LPAR6, ADGRE5, IL10, and IL6 in scRNA-seq and the TARGET osteosarcoma cohort." (PMID 41502512, 2025). "Similar to CRP, elevated ESR is likely driven by proinflammatory cytokines such as IL-6 and TNF-α, which are known to play a role in osteosarcoma pathogenesis." (PMID 40926779, 2025). "Cytokine profiling has identified inflammatory mediators such as IL-1Ra, IL-6, IL-8, and TNF-α as prognostic indicators in osteosarcoma, with distinct cytokine endotypes correlating with metastatic risk and survival outcomes." (PMID 40506947, 2025). "Pro-inflammatory cytokines, such as IL-6 and TNF-α, promote tumor cell survival by activating anti-apoptotic pathways, thereby increasing osteosarcoma cells’ resistance to therapeutic interventions." (PMID 39949765, 2025). "The NF-κB pathway significantly affected by inflammatory cytokines during chemotherapy, especially in osteosarcoma, where the TME is abundant in pro-inflammatory cytokines such as TNF-α, IL-6, and IL-1." (PMID 39949765, 2025). "There have been some studies which revealed the involvement of IL6 and STAT 3 in increasing PD-L1 expression in osteosarcoma." (PMID 38434518, 2024). "Many factors that play significant roles in neutrophil migration have been explored in osteosarcoma, including CXCL1, IL-6, CCL2, and so on." (PMID 39582869, 2024). "This study aims to determine the correlation between immunoexpression of STAT3, IL6, and EGFR and immunoexpression of PD-L1 in osteosarcoma patients, while also evaluating their expressions in pediatric and nonpediatric patients." (PMID 38434518, 2024). "The communications between MSCs and osteosarcoma cells have been reported in previous studies, and many factors, including CXCL12, IL-6, and VEGF, have been proven to be included." (PMID 39582869, 2024). "DLGAP5 has been shown to activate the IL-6/JAK2/STAT3 signaling pathway, thereby promoting the proliferation and invasion of osteosarcoma cells." (PMID 37958803, 2023). "It has been shown that DLGAP5 can activate interleukin-6/Janus kinase 2/signal transducer and activator of transcription 3 (IL-6/JAK2/STAT3) signaling pathway thereby promoting the proliferation and invasion of osteosarcoma cells." (PMID 36712920, 2023). "The cytokines VEGF, IL-17, IL-6, IL-8, IL-1Ra, TNF-α, and IL-34 can promote the proliferation of osteosarcoma cells, and TGF-β exerts dual effects on tumors; they inhibit tumor growth in the early stage and promote tumor growth in the late stage." (PMID 35102149, 2022). "Previous reports have shown that the cytokines VEGF, IL-17, IL-6, IL-8, IL-1Ra, TNF-α, IL-34, and TGF-β play a role in the development of osteosarcoma." (PMID 35102149, 2022). "Among these, VEGF, IL-17, IL-6, IL-8, IL-1Ra, TNF-α, and IL-34 can promote cell proliferation in osteosarcoma; only TGF-β has a dual role in the tumor." (PMID 35102149, 2022). "It is described that the tumor maintains the stemness of MSC through the TGF/Smad3 pathway and that osteosarcoma cells, via TGF-β1 secretion, enhance the production of pro-tumorigenic cytokines, such as IL-6, in the nearby stroma." (PMID 36232719, 2022). "RNA-Seq of KDM5A-KO cells indicated that interferon, epithelial–mesenchymal transition (EMT), IL6/JAK/STAT3, and TNF-α/NF-κB pathway were likely involved in the regulation of osteosarcoma cell viability." (PMID 33436536, 2021). "IL6 also increased the expression of intercellular adhesion molecule-1 (ICAM-1) and promoted migration in human osteosarcoma cells." (PMID 33436536, 2021). "It has been found that Interleukin 6 (IL-6) promotes epithelial-to-mesenchymal transition (EMT), stemness and chemoresistance in osteosarcoma cells through the hyperactivation of STAT3 through a mechanism mediated by osteopontin (OPN)." (PMID 34198693, 2021).
osteosarcoma (continued). "The compound inhibited constitutive and interleukin-6-induced STAT3 signaling and diminished the accumulation of STAT3 in the nucleus, blocking STAT3 DNA-binding activity in osteosarcoma cells." (PMID 32703212, 2020). "In summary, we demonstrated the effect of orento in vitro on IL-6, IL-8 secretion, type 1 collagen production and ALP secretion in the human osteosarcoma cell line Saos-2." (PMID 32992711, 2020). "Our study confirmed the involvement of the IL-6/TIMP3/Caspase pathway in vitro and in vivo, and revealed the important role of TIMP3 in cisplatin sensitivity in osteosarcoma." (PMID 29731768, 2018). "Our results indicated that the expression of IL‐6, CXCL5, and CCR5 in osteosarcoma cells was similar to their levels in hFOB1.19 cells." (PMID 29377600, 2018). "After analysis with ImageJ software, one-way ANOVA and the Newman-Keuls multiple comparison test, we found that osteosarcoma cells (SOSP-9607, F5M2 and F4) expressed higher levels of IL-6 than did normal osteoblastic cells (hFOB 1.19) (P < 0.001)." (PMID 26623559, 2016). "We previously demonstrated that IL-6, a major activator of STAT3 signaling, plays an important role in the interaction between MSCs and osteosarcoma cells." (PMID 27340780, 2016). "In conclusion, IL-6 and the activated STAT3 pathway represent novel targets to inhibit tumour self-seeding by CTCs, which has great potential to inhibit osteosarcoma progression and enhance survival." (PMID 26623559, 2016). "Using IL-6 immunocytochemistry, we found that the human osteosarcoma cell line SOSP-9607 and its sublines F5M2 and F4 expressed IL-6." (PMID 26623559, 2016). "Fang and Hahn examined the effects of IL-6 in UMR-106–01 cells, a rat osteoblastic osteosarcoma line, and observed that it suppressed collagen synthesis." (PMID 22474400, 2012). "Furthermore, AGPAT3 knockdown in osteosarcoma cell lines, combined with co-culture experiments, confirmed that LPA regulates TAM-mediated secretion of IL-10 and IL-6 via the LPAR6 signaling pathway." (PMID 41502512, 2025). "Furthermore, radiotherapy has been demonstrated to induce retinoblastoma (RB)‐dependent senescence and the secretion of IL‐6, consequently enhancing immune surveillance by NKT cells in osteosarcoma." (PMID 39270064, 2024). "This study shows that luteolin may regulate multiple signaling pathways by targeting various genes like AKT1, STAT3, IL6, TNF, and VEGFA to inhibit osteosarcoma proliferation and metastasis." (PMID 37749554, 2023). "We found IL-6 and its downstream pathway STAT3 were activated in anlotinib-resistant osteosarcoma." (PMID 37404767, 2023). "To determine whether doxorubicin enhanced TNF-α, IL-6, IL-1β, TGF-β, and IFN-γ expression in osteosarcoma, we treated MG63 and 143B cells as indicated." (PMID 35326493, 2022). "In addition to IL6, IL8 has also been found to be a positive factor in the promotion of osteosarcoma progression by CTCs." (PMID 35720360, 2022). "In response to doxorubicin, IL-1β, but not IL-6, allowed- osteosarcoma cells to promote the expression of PD-L1, and the elimination of IL-1β/IL-1 receptor signaling with IL-1 receptor antagonist reduced PD-L1 expression." (PMID 35326493, 2022). "The influence of cell effects is supported by studies that describe paracrine interactions between MSCs and osteosarcoma cells driving resistance to doxorubicin, whereby MSC-secreted IL-6 protects tumour cells by STAT3 activation from doxorubicin-induced apoptosis in vitro and in vivo." (PMID 34638373, 2021). "IL-6 mediates the dissociation of 14-3-3 from ASK1 (through Ser966 dephosphorylation), which leads to abnormal ASK1/p38 signaling and consequently to VEGF upregulation and angiogenesis elevation in human osteosarcoma." (PMID 34948191, 2021).